NOD1 (nucleotide binding oligomerization domain containing 1)
Diseases named in the same sentence as NOD1 in open-access papers (continued):
Sharing a sentence is not in itself a finding about the gene and the disease.
Obesity (continued). "Together, the data are compatible with a protective function of NOD1 against low-grade inflammation and obesity under nutritional conditions enriched in saturated lipids." (PMID 32704052, 2020). "The idea that lipids and bacterial-derived molecules cooperate in the induction of ‘metabolic inflammation’ and obesity comes from the fact that particularly NOD1 is overexpressed and activated in adipose tissue in response to these challenges." (PMID 32704052, 2020). "The contribution of the nucleotide-binding oligomerization domain protein NOD1 to obesity has been investigated in mice fed a high fat diet (HFD)." (PMID 32704052, 2020). "We now provide in vivo evidence that NOD1 expression is decreased in two different mouse models of obesity, suggesting that reduced NOD1 expression is a component of adipose tissue expansion." (PMID 29038790, 2017). "It is possible that many levels of regulation for NOD1-mediated sensing of PGN take place during obesity, since NOD1 transcripts were increased in epididymal adipose tissue of mice fed with high-fat diet." (PMID 23482058, 2013). "However, despite its established role in metabolic and inflammatory pathways, the contribution of NOD1 in acute lung injury during obesity remains insufficiently investigated." (PMID 40616268, 2025). "Obesity itself alters gut microbiota composition and increases systemic levels of NOD1‐activating muropeptides, which may enhance pulmonary NOD1 signaling during acute lung injury." (PMID 40616268, 2025). "In addition, recent data point out the protective function of NOD1 reducing low-grade inflammation and thereby obesity development." (PMID 38397943, 2024). "NOD1 and NOD2 can balance pathogenic and protective immune responses during obesity." (PMID 39507249, 2024). "During obesity, Nod1−/− mice had just lower arginase activity in the BAL." (PMID 39507249, 2024). "Based on these differences, NOD1 inhibition might serve as a therapeutic option to alleviate obesity-induced glucose intolerance, while NOD2 stimulation might favor blood glucose homeostasis." (PMID 37239938, 2023). "Interestingly, Nod1−/− mice showed accelerated diet-induced obesity, demonstrating the involvement of this PRR in metabolism and body weight regulation and becoming a good target for immunonutrition." (PMID 34066406, 2021). "In our study, HFD-induced reductions in Bifidobacterium, which could explain increased lipid absorption leading to obesity and adiposity, although these effects were identified in both WT and NOD1 KO and attributed exclusively to the HFD." (PMID 32704052, 2020). "If similar decreases in NOD1 expression or activity were found in humans, with decreases in thyroidal FT4 and FT3, this would indicate the early involvement of the thyroid in pathological events, such as obesity associated to alterations in this NLR." (PMID 32704052, 2020). "However, under a HFD regimen, the rise in REE during the darkness period is lesser than in the WT animals, contributing to the increased obesity in NOD1 KO mice vs. the same genotype in CHD." (PMID 32704052, 2020). "Indeed, experiments using germ-free mice show protection against HFD-induced obesity in NOD1 KO animals, although this phenotype is suppressed when mice are housed under conventional conditions and the gut becomes colonized." (PMID 32704052, 2020). "We provide evidence of different mechanisms that could explain this accelerated obesity of NOD1 KO mice fed HFD." (PMID 32704052, 2020). "We now sought to determine if bacterial PGN sensed by NOD1 or NOD2 could alter other metabolic defects seen during obesity." (PMID 24828250, 2014). "Testing NOD1 in this neutrophil‐driven model of acute lung injury allowed us to investigate its function in a mechanistically distinct setting from our previous work and to understand its potential as a context‐specific modulator of lung inflammation during obesity." (PMID 40616268, 2025).
Obesity (continued). "Moreover, one of the key players of this early obesity onset is a dysregulation in the metabolism and release of thyroid hormones leading to reduced energy expenditure, which represents a new role for these hormones in the metabolic actions controlled by NOD1." (PMID 32704052, 2020). "Indeed, our data suggest an interplay between NOD1 activity, microbiota and thyroid hormone function that might help to unravel unexpected obesity-related pathologies in humans." (PMID 32704052, 2020). "Therefore, intestinal epithelial NOD1 may play a protective role in strengthening the gut barrier and restricting this bacterial influx in obesity." (PMID 32704052, 2020). "Our study describes that NOD1 and NOD2 have distinct roles in allergic lung inflammation during diet-induced obesity." (PMID 39507249, 2024). "Despite some similar signaling pathways, NOD1 and NOD2 can produce divergent metabolic and immunometabolism outcomes, including regulation of blood glucose and adipose tissue inflammation during obesity." (PMID 39507249, 2024). "So, in brown AT, in addition to the inhibition of differentiation, NOD1 activation reduces energy expenditure by decreasing UCP-1 expression, highlighting a possible contribution of NOD1 to obesity not only in white but also in brown AT." (PMID 37239938, 2023). "Increased expression of NOD1 and/or NOD2 has been reported in a range of human metabolic diseases, including obesity, diabetes, non-alcoholic fatty liver disease, and metabolic syndrome." (PMID 33503814, 2021). "While NOD1 and NOD2 have been demonstrated to alter systemic metabolic phenotypes (e.g., obesity, insulin sensitivity, etc.), there is also evidence that they play a role in cellular metabolic stress signaling." (PMID 33503814, 2021). "Ucp1 mRNA was decreased to 60% in NOD1 mice on HFD, which agrees with the observed obesity under HFD in NOD1 KO mice." (PMID 32704052, 2020). "However, we hypothesize that obesity‐induced modifications, combined with the absence of NOD1 itself, may lead to compensatory activation of alternative PRRs, as suggested by the increased pulmonary expression of Nod2 observed in NOD1‐deficient mice." (PMID 40616268, 2025). "We were surprised by our previous findings showing that NOD1 deletion during obesity did not significantly affect allergic pulmonary inflammation in a model of OVA‐induced asthma, which primarily involves type 2 immunity and eosinophilic infiltration." (PMID 40616268, 2025). "Herein, we demonstrated that the RIP2-TAK1 signaling pathway in macrophages is activated by DCLK1 during obesity, and this activation is independent of NOD1/2." (PMID 37443105, 2023). "Increased expression of NOD1 and/or NOD2 has been reported in a range of human metabolic diseases, including obesity, diabetes, non-alcoholic fatty liver disease (NAFLD), and metabolic syndrome, or chronic diseases associated with mitochondrial dysfunction, such as IBD." (PMID 33503814, 2021). "The HFD used promoted a modest increase in body weight of the WT animals (9.8% increase after 6 weeks); however, in the absence of NOD1 the body weight gain was 33.3% during this period, reflecting this obesity in adipose tissue and in the liver." (PMID 32704052, 2020). "Here we provide a new piece of knowledge since our animals deficient in NOD1 and fed a HFD for 6 weeks, despite an evident obesity, are not resistant to insulin and exhibit an improved glucose tolerance test when compared with the WT counterparts." (PMID 32704052, 2020). "In this work, we show that under a standard CHD, the absence of NOD1 does not alter lipid metabolism nor promote obesity, as deduced by the presence of normal adipose tissue and complete absence of liver steatosis in these mice." (PMID 32704052, 2020). "It is not yet clear if Nod1 or Nod2 immunometabolism is more important in glucose control during obesity." (PMID 28484277, 2017).
Obesity (continued). "Therefore, the deletion of NOD2, but not NOD1, increased inflammation in the lung parenchyma during obesity." (PMID 39507249, 2024). "Therefore, NOD1 and NOD2 can have opposing roles in aspects of inflammatory lung disease, but it was not clear if NOD1 or NOD2 influenced the protective effect of obesity on allergenic lung inflammation." (PMID 39507249, 2024). "This has fostered the concept that NOD2 may provide immune tolerization effects to dampen inflammation, but still, it is not clear how NOD1 or NOD2 influences allergic lung inflammation during obesity." (PMID 39507249, 2024). "Absence of NOD1 accelerates obesity as early as 2 weeks after feeding a HFD." (PMID 32704052, 2020). "However, NOD1 had little or no role in altering lung inflammation during diet-induced obesity." (PMID 39507249, 2024).
breast carcinoma (21 papers, 2013 to 2025). "A number of immune-related molecules have already been associated to the onset and progression of breast cancer, including NOD1 and NOD2, innate immune receptors of bacterial-derived components which activate pro-inflammatory and survival pathways." (PMID 30791886, 2019). "NOD1 stimulation induces apoptosis of MCF-7 breast carcinoma cells, and NOD1-deficient MCF-7 cells generate larger tumors when injected into immunocompromised mice." (PMID 24681825, 2014). "Herein, it was shown that NOD1-deficient MCF-7 breast cancer cells were resistant to iE-DAP and cycloheximide mediated cell death." (PMID 25071785, 2014). "Furthermore, CASP8 (2%), NLRC4 (1%), NLRP3 (1%), NLRP2 (1%), PLCG1 (1%), NLRP1 (1%), NLRP7 (1%), SCAF11 (1%), GSDMC (1%), and NOD1 (1%) occurred somatic mutations as well as most of them had high frequencies of CNV in breast cancer." (PMID 34589498, 2021). "To explore the potential mechanisms underlying the role of high NOD1 expression in promoting breast cancer cell stemness and chemoresistance, we analyzed the RNA-seq data in NOD1-overexpressing breast cancer cells and performed GSEA." (PMID 38437016, 2024). "Taken together, these results indicate that the combined presence of ETBF and NOD1 expression in tumors contributes to the tumor-malignant phenotype of breast cancer and enrichment of BCSCs." (PMID 38437016, 2024). "NOD1 was highly expressed on ALDH+ breast cancer stem cells (BCSCs) and cooperated with GAK to phosphorylate NUMB and promote its lysosomal degradation, thereby activating the NOTCH1-HEY1 signaling pathway to increase BCSCs." (PMID 38437016, 2024). "The presence of ETBF and NOD1 expression in tumors predicted a poor response to chemotherapy in breast cancer patients." (PMID 38437016, 2024). "In this study, we demonstrated that ETBF presence and NOD1 expression contribute to chemoresistance in breast cancer." (PMID 38437016, 2024). "GAK-knockdown in NOD1-overexpressing breast cancer cells significantly inhibited NOD1-induced cell proliferation, suppressed BCSC enrichment and re-sensitized cells to DTX, suggesting that GAK-knockdown reversed phenotype induced by NOD1-overexpressing." (PMID 38437016, 2024). "The data obtained suggested that ETBF and NOD1 in tumors are potential therapeutic targets to overcome breast cancer chemoresistance." (PMID 38437016, 2024). "To examine the therapeutic effect of NOD1 inhibition and ETBF clearance in breast cancer, we first treated breast cancer cells with the NOD1 inhibitor Nodinitib-1 alone or in combination with DTX." (PMID 38437016, 2024). "Similar results were obtained in NOD1-overexpressing breast cancer cells at a higher IC50 than that observed in EM cells." (PMID 38437016, 2024). "In this study, we showed that ETBF infection significantly promoted breast cancer cell stemness in a NOD1-dependent manner." (PMID 38437016, 2024). "Clinically high expression of NOD1 was linked to shorter over survival (OS), relapse-free survival (RFS), and distant metastasis-free survival (DMFS) of breast cancer patients who received neoadjuvant chemotherapy." (PMID 38437016, 2024). "Another in vitro cellular experiment showed that in the ER-positive MCF7 breast cancer cell line, NOD1 upregulation promoted RIP2 and caspase-8 mediated apoptosis and decreased estrogen-induced cell proliferation response." (PMID 37020871, 2023). "NOD1 plays an important role in the development of colon cancer and breast cancer, and its dysregulation drives the progression of CIN to cervical cancer." (PMID 35130902, 2022). "This is consistent with the increased expression of NOD1 observed in colon cancer metastasis and breast cancer cell lines." (PMID 35130902, 2022). "Several studies have indicated that NOD1 plays an important role in the development and progression of gastric cancer, colon cancer, breast cancer and cervical cancer." (PMID 34627252, 2021).
breast carcinoma (continued). "The abnormal expression of NOD1 and RIP2 has been associated with cell apoptosis and development of breast cancer and oral cancer." (PMID 32021648, 2020). "Several studies suggested that NOD1 plays crucial role in the development of cancers, such as gastric cancer colorectal cancer, and breast cancer." (PMID 32021648, 2020). "And as reported in a previous literature, NOD1 was found to have tumour suppressor activity toward estrogen receptor (ER)-dependent breast cancer in a xenograft model." (PMID 33023525, 2020). "Next, human breast cancer epithelial cell lines MCF-7 overexpressing NOD1 or NOD2 have been used in a similar fashion for characterization of NOD1/2 ligands." (PMID 31480368, 2019). "In the estrogen-dependent MCF7 breast cancer cell line, NOD1 activation was shown to promote RIP2 and caspase 8-mediated apoptosis and to reduce estrogen-induced proliferative responses in vitro." (PMID 29615116, 2018). "NOD1 has also been suggested to be a tumor suppressor gene in a model of estrogen receptor-dependent breast cancer." (PMID 29615116, 2018). "While most investigations have been focused on the role of NOD1 in models of intestinal tumorigenesis, one report provided experimental evidence for the protective role of NOD1 in breast cancer." (PMID 25071785, 2014). "We therefore explored whether GAK regulated NUMB by phosphorylation in NOD1-overexpressing breast cancer cells." (PMID 38437016, 2024). "To determine whether ETBF or BFT-1 influenced the interaction between NOD1 and GAK, we transiently transfected breast cancer cells with FLAG-tagged NOD1 or GAK." (PMID 38437016, 2024). "To determine whether NOD1 increased breast cancer cell stemness by positively regulating BCSC symmetric division, we assessed the pattern of BCSC division in vitro by paired-cell analysis and immunostaining of the NUMB protein." (PMID 38437016, 2024). "We next investigated the biological functions of NOD1 in breast cancer cells and found that NOD1-overexpressing in breast cancer cells significantly promoted cancer cell proliferation, increased the ALDH+ BCSC population, and upregulated stemness gene expression." (PMID 38437016, 2024). "Interestingly, we found BFT-1 increased the steady-state level of NOD1 protein in breast cancer cells in a dose- and time- dependent manner." (PMID 38437016, 2024). "NOD1 was found involved in TNF-induced apoptosis and the overexpression of NOD1 could enhance sensitivity to TriDAP-induced apoptosis in breast cancer cells." (PMID 32021648, 2020). "In fact, NOD1 and NOD2 have already been associated to increased risk of breast cancer." (PMID 30791886, 2019). "Bioinformatics enrichment analysis revealed upregulation of proteins in the NOD-like receptor signaling pathway, including several heat shock proteins and SGT1, which in turn interacts with HSP90 and is essential for NOD1-mediated cytokine production and apoptosis in breast cancer cells." (PMID 30791886, 2019). "In addition, NOD1 downregulation enhanced the multiplication of breast cancer cells." (PMID 37020871, 2023). "Mechanistically, the bacterial toxin BFT-1 directly binds to and stabilizes the innate immune sensor NOD1 protein, which is preferentially overexpressed in ALDH+ breast cancer stem cells (BCSCs)." (PMID 40444051, 2025). "NOD1 inhibition and ETBF clearance increase the chemosensitivity of breast cancer by impairing BCSCs." (PMID 38437016, 2024). "We observed that NOD1-overexpressing significantly inhibited NUMB protein expression and increased NICD1 levels in breast cancer cells." (PMID 38437016, 2024). "Treatment of breast cancer cells with 10 nmol/L BFT-1 significantly downregulated NUMB and increased NICD1 levels in NOD1-overexpressing cells." (PMID 38437016, 2024). "In breast cancer cells treated with CHX, the half-life of the NUMB protein was significantly decreased in NOD1-overexpressing cancer cells." (PMID 38437016, 2024).